CD47 (CD47 molecule)
Diseases named in the same sentence as CD47 in open-access papers (continued):
Sharing a sentence is not in itself a finding about the gene and the disease.
tumor (continued). "The main objective of this study was to investigate the relationship between the expression levels of Trop-2, CD47, and CD163, as assessed by immunohistochemistry in tumor tissue, and clinical outcomes and survival in TNBC, which is characterized by an aggressive clinical course and poor prognosis." (PMID 39857116, 2025). "Furthermore, immunofluorescence analysis of tumour tissues from tumour-bearing mice confirmed the coexpression of CXCR2, CPT1A, and CD47, supporting a functional connection between the IL-8/CXCR2 pathway and metabolic regulation." (PMID 41163221, 2025). "When combined with standard treatments such as temozolomide or radiotherapy, anti-CD47 therapies have produced synergistic anti-tumor effects without damaging non-tumoral neural tissues." (PMID 40867316, 2025). "As for PDPN targeting, the relief of the inhibitory signal delivered through the CD47-SIRP-α binding on macrophages could generate a pro-inflammatory TME favoring the anti-MB immune response, as indicated for other tumor types." (PMID 40677711, 2025). "CD47 is widely expressed on the surface of tumor cells and serves as a major mediator of “nonphagocytic” signals." (PMID 41383334, 2025). "To bolster tumor penetration and reduce phagocytosis, we engineered a cationization-enabled transcytosis machinery by installing an ultra-pH-sensitive azepane (AZE) probe into paclitaxome and masked nanovesicle surface with a CD47 ‘self’ peptide (CD47p)." (PMID 40841472, 2025). "Importantly, when combined with a CD47 nanobody, IR700@Nb289‐OMVs markedly extended survival and partially eradicated tumours in subcutaneous and metastatic (lung and peritoneal cavity) CRC mouse models." (PMID 40240911, 2025). "For example, The “Do not eat me” signal formed by the binding of the CD47 protein, which is expressed on the tumor cells, to signal-regulatory protein alpha (SIRPα), which is expressed on myeloid cells, enables tumor cells to evade immune surveillance." (PMID 40461514, 2025). "The expression levels of CD47 in the cell lines used in this study were generally lower in the tumor-derived cell lines than in the non-tumor-derived cell lines (left)." (PMID 39744689, 2025). "These challenges do not negate CD47 as a therapeutic target; rather, they highlight the need for more refined approaches that integrate tumor context, rational combinations, and biomarker-driven precision." (PMID 41179296, 2025). "Disrupting the CD47-SIRPα axis enables macrophage phagocytosis, induces phenotype switch from M2 to M1 TAMs, reduces CAR cell therapy resistance, and improves NK cell anti-tumor activity." (PMID 41511303, 2025). "Unlike antagonistic molecules targeting CD47 or SIRPα directly, small-molecule inhibitors for this pathway do not compete with natural binding partners in the tumor microenvironment." (PMID 40589735, 2025). "Consistent with preclinical and clinical studies, we found that targeting PD‐L1 alone was not effective in reducing tumor burden, whereas CD47 treatment sensitized the tumor to the immune system and significantly reduced tumor growth." (PMID 39888280, 2025). "Silencing TUG1 inhibits tumor growth and metastasis, enhances the infiltration of CD8+ T cells and M1 macrophages, and activates CD8+ T cells through PD-L1 while promoting macrophage phagocytosis via CD47." (PMID 40352941, 2025). "Tumor bearing mice were treated with WP1066 alone, anti-CD47 alone or WP1066 + anti-CD47." (PMID 40529368, 2025). "Rather than utilizing extensive cell-cell communication, metastatic tumor cells are predicted to employ a dominant immune-evading signaling axis through the upregulation of the “do not eat me” ligand CD47." (PMID 41450739, 2025). "Intratumoral administration of anti-CD47 antibody alone did not mediate a significant survival benefit relative to PBS-treated mice nor did it delay tumor growth." (PMID 41322194, 2025).
tumor (continued). "Particularly, the absence of CD47 expression on ECs markedly boosts angiogenesis, thereby effectively mitigating hypoxia-induced tumor necrosis and expediting tumor progression." (PMID 41300494, 2025). "Here it is found that TRAF2 bound to the C‐terminal of CD47 cytoplasmic fragment and induced its ubiquitination, leading to inhibition of CD47 autophagic degradation by disrupting its binding to LC3, which in turn inhibited macrophage phagocytosis and promoted tumor immune escape." (PMID 39665172, 2025). "Given the observed coexpression of CXCR2 and CD47, we propose that the IL-8/CXCR2 pathway may regulate CD47 expression, thereby impairing TAM recruitment and increasing tumour immune evasion." (PMID 41163221, 2025). "While CD47 blockade has demonstrated efficacy in hematologic malignancies, its application in solid tumors is hindered by the antigen sink effect and lack of tumor selectivity." (PMID 41402667, 2025). "Current evidence points towards the importance of tumor-initiating receptor-ligand interactions, e.g., FcγR-antibody complexes, TCR-MHC engagement, CD47-SIRPα signalling, cell intrinsic regulators such as CH25H mediated cholesterol metabolism and ATF3 transcriptional control within the TME." (PMID 41181711, 2025). "In summary, CD47 blockade with NDV failed to enhance APC function or CD8 T cell proliferation but increased PD-1 on CD8 T cells alongside high tumor PD-L1." (PMID 41322194, 2025). "Tumor cells overexpress CD47, a transmembrane protein, to bind SIRPα and send a ‘do not eat me’ signal, preventing phagocytosis and allowing tumors to avoid immune destruction." (PMID 40070841, 2025). "MSF@CCM combines the biomimetic properties of CCM for immune evasion by mimicking “self” markers (e.g., CD47) and tumor targeting through homotypic cell recognition, achieving 2.0-fold higher tumor retention than non-camouflaged nanomedicine." (PMID 40274835, 2025). "TUG1, upregulated by METTL3-mediated m6A, regulates PD-L1 and CD47 by sponging miR-141/miR-340 and interacting with YBX1; its knockdown inhibits tumor growth, enhances CD8+T/M1 macrophage infiltration, activates CD8+T via PD-L1, and boosts macrophage phagocytosis through CD47." (PMID 40352941, 2025). "CD47, an innate immune checkpoint frequently overexpressed in CRC, serves as a major “don’t eat me” signal, by binding to SIRPα on the surface of macrophages, thereby inhibiting phagocytosis and facilitating tumor immune evasion." (PMID 41514569, 2025). "They do not correlate with CD47 expression; however, high CD163+ infiltration is associated with tumor diameter and a high pT-stage." (PMID 40427098, 2025). "Compared with untreated controls, tumour-bearing mice treated with navarixin—an orally bioavailable small-molecule antagonist of CXCR1/2—or with thrombospondin-1 (TSP-1), which simultaneously blocks CD47 on tumour cells and CD36 on macrophages, presented significantly reduced tumour volumes." (PMID 41163221, 2025). "CD47, a key cell surface receptor, exhibits significant overexpression in tumor tissues, including PDAC, compared to non-tumor tissues, as revealed by TCGA database analysis using GEPIA." (PMID 41350707, 2025). "Mice that had received NDV and CD47 blockade appeared to have delayed tumor growth as well relative to those that were not treated." (PMID 41322194, 2025). "HCB101 demonstrates high-affinity binding to CD47, robustly promotes macrophage-mediated phagocytosis of tumor cells without affecting red blood cells and exhibits unique advantages over current CD47-targeting agents, including Hu5F9-G4, TTI-622, and ALX148." (PMID 41131565, 2025). "Inhibition of this pathway suppresses CD47 membrane localization on tumour cells, thereby attenuating the “do not eat me” signal and restoring macrophage-mediated phagocytosis." (PMID 41163221, 2025). "In the complete tumor resection model, no tumor recurrence was observed postoperatively, indicating that CD47‐targeted OMI can improve tumor detection." (PMID 40385528, 2025).
tumor (continued). "As expected, in this work, anti-CD47 antibody (CC2C6) showed strong binding and hemagglutination with RBCs, whereas the phenomena of anti-CD47 nanobodies hu404 were negligible; meanwhile, hu404-hFc fusion still maintain the binding ability to tumor cells." (PMID 38783333, 2024). "An interesting report had highlighted that the role of Glutaminyl cyclase isoenzyme (QPCTL) is critical for pyroglutamate formation on CD47 at the SIRPα binding site and inhibition of QPCTL activity enhances antibody-dependent cellular phagocytosis and cellular cytotoxicity of tumor cells." (PMID 39318624, 2024). "Moreover, compared with anti-CD47 (5F9) and daratumumab, ISB 1442 also mediates increased phagocytosis of T-ALL and AML tumor cells in cell lines with reduced CD38 and CD47 expression." (PMID 38983860, 2024). "SL172154 is a CD47 inhibitor that has enhanced pro-phagocytic signals on leukemic stem cells/blats coupled with CD40L to enhance antigen presentation and further enhance tumor cell killing." (PMID 39697225, 2024). "The observation that CD47 × PD‐L1 BisAb treatment elicited enhanced CD8+ TIL formation and function led us to ask whether tumor protection observed upon CD47 × PD‐L1 BisAb treatment was CD8+ T cell dependent." (PMID 39584189, 2024). "In combination with serial deletions of CD47 promoter, we defined the minimal DNA region required for its activation, as well as, specific DNA locations within that region, which are preferentially occupied by NRF-1 in tumor cells." (PMID 39742254, 2024). "However, the combination of CD47 Ab and CPMV has a synergistic potential to induce tumor cell death by activating macrophages compared to monotherapy." (PMID 38832992, 2024). "Notably, the combination of anti-CD47 Ab and anti-CTLA4 Ab resulted in a more substantial delay in tumor growth than either of the single-agent treatments." (PMID 38398223, 2024). "We have focused on the two immune checkpoints, PD-1/PD-L1, the “Do not kill me signal”, and CD47/SIRPα, the “Do not eat me signal”, to examine the kinetics of tumor immunity in the tumor microenvironment of OSCC." (PMID 38612630, 2024). "We found that CD47 × PD‐L1 BisAb treatment resulted in robust CD8+ T cell responses, including the induction of tumor‐resident CD8+ T cells that exhibited functionally superior anti‐tumor immunity when compared to anti‐PD‐L1 monotherapy." (PMID 39584189, 2024). "Given that we have demonstrated a relatively high expression of CD47 independent of tumor grade, this finding serves as an initial motivation for pursuing further investigations and exploring the potential of targeting the CD47/SIRP-α pathway." (PMID 38493445, 2024). "The combination of DSF/Cu and CD47 blockade further promoted the maturation of DCs and enhanced the cytotoxicity of CD8+ T cells, which could effectively activate the anti-tumor immune response and inhibit tumor growth." (PMID 39482784, 2024). "Engagement of innate and adaptive immune checkpoint molecules via CD47 × PD‐L1 BisAb treatment resulted in robust CD8+ T cell responses, including the induction of tumor‐resident CD8+ T cells that exhibited functionally superior anti‐tumor immunity." (PMID 39584189, 2024). "Antibody-drug conjugates (ADCs) utilizing mertansine and anti-CD47 mAb for TNBC treatment demonstrated potent tumor suppressive activity without systemic immune toxicity." (PMID 39040441, 2024). "By overexpressing CD47 protein on the BC cell membrane and binding it to SIRP-α on the surface of macrophages, the nanoparticle enzyme was able to evade phagocytosis by macrophages, prolong its circulation time in the bloodstream, and enrich in tumor tissues." (PMID 39482784, 2024). "In contrast, among non-MYCN amplified tumors, high expression of CD47 was detected on both cell membrane and neurites of the tumor cells." (PMID 38920727, 2024).
tumor (continued). "This research demonstrated that LINC00460 promoted CRC cell immune escape by increasing the expressions of MYC, CD47 and PD-L1 in CRC cells and remodeling the CRC tumor-inhibitory immune microenvironment, thereby promoting the occurrence and development of CRC tumors." (PMID 39135122, 2024). "Unlike stimulating T-cell activity, the CD47–Signal regulatory protein alpha (SIRPα) axis functions as a regulatory point for tumor phagocytosis." (PMID 38543240, 2024). "The differential requirement of tumor cell IFNGR signaling for CTLA-4 or PD-1 ICB and IFNAR signaling for CD47-SIRPα ICB may be due to the difference of their primary effector targets." (PMID 38982116, 2024). "Blocking CD47 signaling with an oncolytic adenovirus carrying a SIRPα-IgG1Fc fusion gene (SG635-SF) significantly increases macrophage infiltration into the tumor and suppresses tumor growth in OC mice." (PMID 39513610, 2024). "The categorization of CD47 positivity was as follows: 0 (no staining of tumor cells), 1 + (less than 1/3 of tumor area positive), 2 + (between 1/3 and 2/3 of tumor area positive), and 3 + (more than 2/3 of tumor area positive for CD47)." (PMID 38493445, 2024). "The combination of CD47 mAb with trastuzumab not only significantly reduced the growth of HER2+ breast tumors resistant to ADCC but also enhanced the efficacy of trastuzumab, leading to complete tumor regression." (PMID 39040441, 2024). "To minimize immune rejection faced by UCAR-T cells in the tumor microenvironment (TME), we overexpressed CD47, which enables tumor cells to evade immune surveillance, and has been shown the potential to protect CAR-T cells from clearance by macrophages and NK cells." (PMID 39906740, 2024). "TSP-1 also blocks the CD47-SIRPα “do-not-eat-me” macrophage checkpoint to enable phagocytosis of tumor cells." (PMID 38218979, 2024). "Because CD47 is ubiquitously expressed throughout the body, the lack of tumor selectivity leads to undesirable side effects such as anemia and thrombocytopenia." (PMID 38786045, 2024). "Similarly, detachable immune liposomes loaded with paclitaxel and anti-CD47 antibody have been developed for targeted chemotherapy against TNBC, resulting in improved antitumor efficacy against TNBC and inhibited tumor recurrence." (PMID 38894873, 2024). "RRx-001, a CD47 inhibitor, blocks the “do not eat me” signaling pathway by downregulating the CD47-SIRPα axis, thus preventing tumor cell immune evasion." (PMID 39664519, 2024). "Knockdown of TUG1 inhibited tumor growth and metastasis, increased the infiltration of CD8+ T cells and M1‐like macrophages in tumors, promoted the activation of CD8+ T cells through PD‐L1, and improved the phagocytosis of macrophages through CD47." (PMID 38981064, 2024). "The CD47 molecule, often referred to as the “do not eat me” signal, is frequently overexpressed in tumor cells." (PMID 38493445, 2024). "A study showed that the expression of TSP-1 and CD47 is increased in human malignant melanoma tumor tissue, and targeting the TSP-1/CD47 pathway may preserve CD8+ T-cell activation, proliferation, and bioenergetics to alleviate the tumor burden." (PMID 38516004, 2024). "Notably, in vitro blockade of CD47 on human LMS cell lines and in LMS mice model resulted in increased phagocytosis and reduced tumor size respectively." (PMID 38493445, 2024). "We show that tumor cells have an increased expression of several markers (CD47, IL7R, NKG7, CD80, CD84, CSF1R, NLRC5/CITA, CD2 and IRF3) that may be involved in regulating the level of immune infiltration and the effect on tumor immunity." (PMID 39001353, 2024). "In addition, we evaluated the effect of combining Anti-CD47 and Anti-CTLA4 therapy on tumor vascular normalization." (PMID 38398223, 2024). "CD47, known as the “do-not-eat-me” signal is widely expressed on membrane of various cells including tumor cells." (PMID 39003350, 2024). "We herein demonstrate that XVir-infected tumor cells upregulate both CALR and CD47." (PMID 38357194, 2024).
tumor (continued). "This strategy, which we also call “partially harmful action to promote the greater good”, creates a metastatic tumour microenvironment (TME) through MLKL-driven necroptosis, stimulating the ‘dont eat me’ signal (CD47) and METs formation to facilitate tumour metastasis." (PMID 39025845, 2024). "We examined the immune status of the OSCC tumor microenvironment by focusing on two immune checkpoints, PD-1/PD-L1, the “Do not kill me signal”, and CD47/CD11c, the “Do not eat me signal”." (PMID 38612630, 2024). "For example, SIRPA interacts with CD47 to provide a “do not eat me” signal, helping dormant tumor cells evade macrophage-mediated phagocytosis." (PMID 39273449, 2024). "In terms of tumour size control, when MLKL-overexpressing KPC cells were subcutaneously transplanted into C57BL/6 mice, the combination regimen achieved the greatest improvement in tumour size control and survival, surpassing that of GW or CD47 blockade alone." (PMID 39025845, 2024). "Similarly, clinical approaches targeting the CD47 “don’t eat me” signalling, in combination with the anti-CD20-antibody rituximab, demonstrate increased macrophage activity and phagocytosis of MCL tumour cells." (PMID 38566987, 2024). "No major ADCC was detected in normal cells expressing CD47, suggesting that the BsAbs exhibited less on-target, off-tumor toxicity." (PMID 38983860, 2024). "These engineered exosomes possess evasion capabilities against phagocytosis, attributed to the abundant CD47 proteins from RBC membranes, alongside specialized tumor-homing properties conferred by cancer cell-derived proteins, including EpCAM, Galectin 3, and N Cadherin." (PMID 38542268, 2024). "For example, the cluster of differentiation 47 (CD47), known as the “do-not-eat-me” signal is widely expressed on the membrane of tumor cells." (PMID 39003350, 2024). "Because VT1021 does not target a specific mutation in tumor cells but rather induces TSP-1 that inhibits tumor growth via binding to CD36 and CD47 on the surface of tumor cells, it is critical to identify patients that express sufficient levels of these receptors to maximize its anti-tumor activity." (PMID 39627379, 2024). "An alternate hypothesis is suggested by an analysis presented here of transcripts coexpressed with CD47 mRNA in TCGA RNAseq data for 29 tumor types, which identified intraflagellar transport-57 (IFT57) as a top CD47-coexpressed gene." (PMID 39201643, 2024). "Thus, CD47, CD68, and CD163 not only serve as prognostic indicators but also represent promising targets for novel cancer therapies designed to modulate the tumor immune microenvironment." (PMID 39682556, 2024). "Furthermore, tumor cells were infected and studied for the surface expression of the ‘eat-me’-signal calreticulin (CALR) and the ‘don’t-eat-me’-signal CD47." (PMID 38357194, 2024). "Research has indicated that CD47 and CD96 might alter fatty acid oxidation and mediate immune evasion, thereby enhancing tumor radiotherapy resistance." (PMID 38291470, 2024). "Among 50 patients, 24 cases exhibited negative expression and 26 cases exhibited positive expression of CD47 in tumor tissues, while in adjacent non-cancerous tissues, 16 cases were negative and 4 cases were positive for CD47 expression." (PMID 39652550, 2024). "Therefore, CD47 blockade promotes the phagocytic ability of macrophages in the TME and contributes to tumor immunotherapy." (PMID 38383737, 2024). "Another novel strategy uses anti-CD47 antibodies that block the “do not eat me” CD47 and signal regulatory protein alpha (SIRPα) interactions that allow for tumor cell evasion of phagocytosis." (PMID 38612926, 2024). "In this study, we designed a novel anti-CD47 antibody, Gensci059, which distinguishes itself from other CD47 targeting agents by lacking hematological liabilities while retaining its anti-tumor properties." (PMID 38429732, 2024).